GATA3 (GATA binding protein 3)
Diseases named in the same sentence as GATA3 in open-access papers (continued):
Sharing a sentence is not in itself a finding about the gene and the disease.
breast carcinoma (continued). "Plasmids containing ERE3 and ERE4 were then transfected into another breast cancer cell line (MCF-7), with or without ERα, GATA-2 or GATA-3." (PMID 27105516, 2016). "In breast cancer alone, up to 50% of patients with Rbness in the absence of RB1 genomic alterations harbored amplifications in PIK3CA, RB (CCND1 and CCNE1), and ER signaling modules (ESR1, FOXA1, and GATA3)." (PMID 40138429, 2025). "GATA3 and SOX10 are useful markers; however, they are not specific for breast cancer." (PMID 40025593, 2025). "Of note, GATA3, SOX10, and mammaglobin are not considered to be specific for breast carcinoma." (PMID 37306115, 2024). "Since GATA3 is an essential gene in ER+ breast cancer cells, we could not use silencing of GATA3 to explore the functional impact of DHT-induced AR-GATA3 interactions on the tumor suppressor role of AR in ER+ breast cancer cells." (PMID 38317241, 2024). "Interestingly, in luminal-subtype breast cancer cells, GLS2 expression is upregulated via GATA-binding factor 3 (GATA3), indicating that its expression pattern differs not only between tissues but, also, between cancer subtypes affecting the same tissue." (PMID 38067269, 2023). "Deregulation of negative feedback between GATA3 and ZEB2 can promote breast cancer metastasis." (PMID 34368227, 2021). "In a subset of breast carcinomas that exhibit high-grade nuclear atypia, and TNBCs, the expressions of breast-specific markers such as GCDFP15, mammaglobin, and GATA3 may be negative or weakly positive." (PMID 32164210, 2020). "Our findings from the integrative databases and bioinformatics analysis of this study suggest that GATA3, but not the other GATA family members, might be a potential prognostic biomarker and target for new therapies for breast cancer." (PMID 30872657, 2019). "Breast markers as NY-BR-1, GATA-3, mammaglobin, and BRST-2 are established tools for labelling primary and metastatic female breast cancer; however, none of them has been sufficiently studied in male breast cancer." (PMID 29116378, 2018). "Thus, the CAMA1 GATA3 mutant knock-in clones do not fully recapitulate the allelic ratio of MCF-7 and most primary breast cancers." (PMID 29262572, 2017). "Moreover, intersection of our identified GRHL2 peaks with published ER⍺ binding events in the same series of luminal breast cancer cells cultured under the same conditions further indicates that GRHL2 binds most of the targets found by us in absence of ER⍺, FOXA1, and GATA3." (PMID 36691073, 2023). "The 479 cases of various types of breast cancers they analysed with IHC showed a high proportion of staining in ER/PR positive (95% of 176), HER2 positive (79% of 67) and TNBCs (81% of both 52 metaplastic and 184 non-metaplastic cases), being more sensitive than GATA3 for this latter subset." (PMID 37012444, 2023). "Additionally, the presence of ER and GATA-3 positivity, along with negative Cudal-type homeobox 2 (CDX2) staining in samples from the cervix, stomach, and rectum, further corroborated the diagnosis of gastrointestinal and cervical metastases originating from breast cancer." (PMID 40989696, 2025). "Moreover, there were higher observed co-expression scores for FOXM1/E2F1, FOXA1/GRHL2, FOXA1/GATA3, suggesting that absence of FOXA1 might contribute to doxorubicin resistance in breast cancer cells through collaboration with the down-regulated GRHL2 and/or GATA3." (PMID 34395436, 2021).
asthma (136 papers, 2008 to 2026). "We will utilize the GATA-3 trial study design as a framework to discuss asthma clinical trial design focused on obesity-associated asthma populations." (PMID 41567689, 2026). "Knockdown of lncRNA-NEAT1 or GATA3 markedly reduced Th2-associated cytokines (such as IL-4, IL-5, and IL-13), and T-cell proliferation, which in turn controlled asthma-related airway inflammation." (PMID 40110044, 2025). "RNA-seq studies of ASM transfected with PGAP3 demonstrated significantly increased levels of genes linked to asthma including GATA3 and ALOX5." (PMID 40131902, 2025). "A decrease in the level of Th1 cells expressing T-bet in the airways of asthma patients caused an increase in GATA-3 expression and Th2 cytokine production." (PMID 39060923, 2024). "The activation status of the asthma-associated single nucleotide polymorphisms (SNPs) enriched region, which is located 900 kb downstream from GATA3 (hG900), and the levels of GATA3 expression were substantially correlated in human peripheral blood T cells." (PMID 38923989, 2024). "Several asthma-associated SNPs have been reported to be located in the region around the Gata3 gene body (16, –18)." (PMID 38923989, 2024). "Asthma-associated single nucleotide polymorphisms (SNPs) are enriched in a region located 926-970 kb downstream from GATA3 in the 10p14 (hG900)." (PMID 38923989, 2024). "Leveraging its improved power, FABIO successfully prioritized multiple potentially causal genes associated with the diseases, including GATA3 for asthma, ABCG2 for gout, and SH2B3 for hypertension." (PMID 39621803, 2024). "This study showed that Cd4-Cre::Acc1fl/fl mice exhibited attenuated AHR and airway inflammation in OVA- and HDM-induced asthma models due to the enhanced apoptosis and loss of Gata3, Il4, and Il13 expression in lung iNKT cells." (PMID 37917548, 2023). "IL-4 and INF-γ levels in asthma patients have been associated with the T-bet/GATA-3 ratio, indicating an immune imbalance in asthma conditions." (PMID 36311189, 2022). "Hypermethylation in GATA3 CpG loci was associated with a decreased risk of asthma at birth, and hypomethylation of IL-13 and interleukin 5 receptor subunit alpha (IL5RA) was associated with an increased risk of asthma in teenagers." (PMID 33732246, 2021). "In contrast, consuming oral contraceptive pills (OCP) at age 18 was reported to increase the predisposition to asthma by impacting the GATA3 gene through the SNP-CpG methylation interplay, which was assessed using peripheral blood cells and saliva samples." (PMID 33781317, 2021). "SIRT1 is a key regulator of GATA3 via its deacetylation, and in T-lymphocytes from patients with severe asthma, a decrease in SIRT1 has been linked to increased expression of IL-4 via increased GATA3 activation." (PMID 32823491, 2020). "For the rs10905284 (GATA3), the asthma risk allele (C; proxy rs3802597; r2=0·93) had an effect on upstream stimulatory factor 1 (USF1) and 2 (USF2) binding in various cell types, including airway epithelium." (PMID 30552067, 2019). "We choose several genes associated with Eos asthma, including Il5RA, GATA3, SATAT5, and SOCS, to identify co-expressed lncRNAs." (PMID 30941157, 2019). "It therefore seems highly likely that the significant effects we observe on asthma risk represent an authentic link to endocrine events via differential methylation of the GATA3 gene." (PMID 25250096, 2014). "Our two-stage model suggests a potential pathway in which sex hormone-related exposures such as OCP use and age at menarche alter the DNA-M within GATA3 to subsequently affect the risk for asthma in girls at 18 years." (PMID 25250096, 2014). "The role of sex hormones and the potential gender-related activity of GATA3 in asthma motivated us to study a possible interaction between oral contraceptives and GATA3 and further its association with asthma." (PMID 25250096, 2014).
asthma (continued). "This study represents the first report of an interaction of genetic variation and DNA-M of GATA3 on the risk for asthma at 18 years, which is modified by the use of OCP and age at menarche." (PMID 25250096, 2014). "The findings suggest a potential pathway in which OCP exposure and age at menarche, presumably via sex hormones, can alter the DNA-M of a GATA3 CpG site, which subsequently, in conjunction with genetic variants, influences the risk of asthma at 18 years." (PMID 25250096, 2014). "In addition, when ASM from non-asthmatics are transfected with PGAP3, the increased levels of PGAP3 increased ASM proliferation and contractility, and increased levels of genes previously linked to asthma including GATA3 and ALOX5." (PMID 40131902, 2025). "Moreover, RNA-seq studies demonstrated that increased PGAP3 expression in ASM increased levels of genes previously linked to asthma including GATA3 and ALOX5." (PMID 40131902, 2025). "In addition, when ASM from non-asthmatics are transfected with PGAP3, the increased levels of PGAP3 increase ASM proliferation and contractility, and increase levels of genes previously linked to asthma including GATA3 and ALOX5." (PMID 40131902, 2025). "Notably, FABIO prioritized multiple candidate genes previously validated for their association with the respective diseases, such as GATA3 for asthma; ABCG2 for gout; and SH2B3 for hypertension." (PMID 39621803, 2024). "GATA3 has been associated with asthma in previous GWAS and acts as a key regulator of T-cell development, Th2 differentiation, and the Th1/Th2 balance to affect asthma risk." (PMID 39621803, 2024). "To investigate the roles of the asthma-associated GATA3 enhancer region in experimental allergic airway inflammation, we first examined the correlation between GATA3 expression and the activation of the hG900 region was analyzed by flow cytometry and ChIP-qPCR." (PMID 38923989, 2024). "By analyzing asthma-associated SNPs from the UK Biobank and GWAS catalog, we confirmed that these SNPs were highly enriched in the region located 926 to 970 kb downstream from GATA3 (referred to as the hG900 region)." (PMID 38923989, 2024). "Hypermethylated GATA3 (location 10p14), a significant regulator of Th2 differentiation, is associated with reduced asthma risk in cord blood, while ZPBP2 (Zona Pellucida Binding Protein 2) hypomethylation results in asthma in a lymphoblastoid cell line at genetic location 17q12-q21." (PMID 34566492, 2021). "Altered expression of the pathogenic mucin MUC5AC potentially contributes to mucus plugging and airway obstruction, GATA3 is a transcription factor linked to the T cell response in asthma and eosinophilia, and the KIAA1109 locus has previously been associated with allergic sensitization." (PMID 32060620, 2020). "Altered expression of the pathogenic mucin MUC5AC potentially contributes to mucus plugging and airway obstruction, GATA3 is a transcription factor linked to the T-cell response in asthma and eosinophilia, and the KIAA1109 locus has previously been associated with allergic sensitisation." (PMID 30552067, 2019). "We found both the KIAA1109 and GATA3 signals were significantly associated with all asthma, including mild asthma (KIAA1109 [proxy rs72687036 coded allele G]: OR 1·06, 95% CI 1·04–1·08; p=3·96 × 10−7; and GATA3 [rs10905284, risk allele C]: OR 1·04, 1·02–1·06; p=2·72 × 10−5)." (PMID 30552067, 2019). "Of the 24 signals, after exclusion of FLG, three were novel for asthma: the sentinel SNP rs10905284 in GATA3 (coded allele A, odds ratio [OR] 0·90, 95% CI 0·88–0·93; p=1·76 × 10−10) and rs11603634 in the MUC5AC region (coded allele G, OR 1·09, 1·06–1·12; p=2·32 × 10−8)." (PMID 30552067, 2019). "Moreover, 163 of those 200 asthma-associated enhancers were Th2-specific and 84 of them contained binding sites for transcription factors involved in T cell differentiation [e.g. GATA binding protein 3 (GATA3), T-box 21 (TBX21) and RUNX3]." (PMID 29796022, 2018).
asthma (continued). "A two-stage model that takes into account genetic variants of the GATA-3 gene, oral contraceptive use, age at menarche and DNA-methylation may explain how sex hormones can increase the prevalence of asthma after puberty." (PMID 28076614, 2017). "In a second stage, we determined whether these CpG sites interact with genetic variants in GATA3 to explain the risk of asthma." (PMID 25250096, 2014). "However a clinical application of CpdA-like molecules for the treatment of inflammatory and Th1-mediated autoimmune diseases must be carefully studied taking into account the association of GATA-3 and IL-5 with allergic diseases such as asthma pathogenesis." (PMID 22496903, 2012). "Th2 cells, defined by the production of IL-4 and the expression of the transcription factor GATA-3, are involved in humoral immunity and eliminate extracellular pathogens but are associated with the development of allergic diseases, such as allergic rhinitis and asthma." (PMID 38139314, 2023). "Therefore, we hypothesize that exogenous or endogenous sex hormone exposure in interaction with genetic variants could be associated with DNA-M of GATA3, which in turn affects the risk of asthma at the age of 18 years." (PMID 25250096, 2014). "Type 2-high asthma is driven by coordinated GATA3-dependent programs in CD4+ T cells and group 2 innate lymphoid cells (ILC2)." (PMID 42094570, 2026). "•The GATA-3 trial framework illustrates how incorporating comprehensive metabolic and inflammatory profiling can improve the design and clinical relevance of asthma trials." (PMID 41567689, 2026). "Elevated GATA3 expression has been observed in the airway epithelium of patients with severe asthma, where it contributes to chronic inflammation and cytokine dysregulation." (PMID 41495895, 2026). "Using the GLP-1R Agonists in the Treatment of Adult, Symptomatic, Obese Asthma (GATA-3) trial (ClinicalTrials.gov NCT05254314) as a conceptual framework, we propose an evolved model for future asthma research." (PMID 41567689, 2026). "Significantly elevated levels of lncRNA-NEAT1 and GATA3 have been found in peripheral blood CD4+ T cells of children with asthma." (PMID 40110044, 2025). "The most prominent asthma-related PGAP3-upregulated gene in ASM found in our data set is GATA3, which was the fourth highest expressed gene (FC = 4.99) induced by PGAP3 in ASM." (PMID 40131902, 2025). "It is known that GATA3 expression is significantly elevated in T cells obtained from airway biopsies of individuals with asthma compared to those from healthy controls." (PMID 40577410, 2025). "Of these 151 PGAP3 upregulated genes found in both our ASM-NA (SC) data set and in the Asthma Reference data set, GATA3 had the highest overall fold change (FC = 4.99)." (PMID 40131902, 2025). "A relevant study confirmed that Lactobacillus plantarum-CQPC11 treatment exhibited excellent effects in alleviating OVA-induced asthma, such as by upregulating T-bet and Foxp3 mRNA levels and inhibiting GATA3 mRNA levels." (PMID 39796399, 2025). "Dietary intake of fiber‐rich foods has been associated with the suppression of airway inflammation, decreased numbers of GATA3 + Th2 cells, and a reduction in FcɛRIα+ eosinophils, suggesting a therapeutic potential in the management of asthma." (PMID 40027477, 2025). "For example, Palikhe and colleagues report that the expression of GATA3 in CD4+ T cells is much higher in severe asthma patients than in those with mild asthma." (PMID 40391221, 2025). "In the largest genome-wide association study to date in moderate-to-severe asthma, Shrineet al. reported that variants in MUC5AC, GATA3 and KIAA1109 were associated with an increased susceptibility to developing moderate-to-severe asthma." (PMID 38609094, 2024). "Expression of GATA3, the master transcription factor of Th2, increased drastically in the asthma group." (PMID 38774754, 2024).
asthma (continued). "The observed reduction in Gata3 expression underscores CycloZ’s impact on the IL-4-Stat6-Gata3 axis, which plays a crucial role in asthma pathogenesis." (PMID 39682780, 2024). "Consistently, fiber rich diet had resolving effects on airway inflammation, mucus production and collagen deposition and local Th2 response during experimental asthma development by reducing antigen presentation of cDC2, the GATA3 Th2 effector cells." (PMID 38757128, 2024). "Asthma is a widespread airway disorder where GATA3-dependent Type-2 helper T (Th2) cells and group 2 innate lymphoid cells (ILC2s) play vital roles." (PMID 38923989, 2024). "The first example is GATA3 associated with asthma (PIP = 1), a gene that resides in the known risk regions of asthma." (PMID 39621803, 2024). "In experimental asthma, in mice fed with high fiber diet, a reduced lung GATA3 + Th2 type mediated inflammation, mucus production and collagen deposition and expression of Fc epsilon receptor Ia (FcεRIa) in eosinophils was observed." (PMID 38757128, 2024). "Another study revealed that genistein modulates the transcription factors STAT6, GATA3, and T-bet, attenuating airway allergic inflammation in a murine asthma model." (PMID 39263346, 2024). "GATA-3 is known to regulate IL-5 expression which is responsible for eosinophilic inflammation in asthma." (PMID 37316684, 2023). "In summary, we found that BGE exerts anti-inflammatory activity both in vitro and in vivo by reducing the activation of PKCθ and asthma-associated transcription factors (NFAT, NF-κB, STAT6, and GATA3)." (PMID 37569348, 2023). "Increased expression of USP21 has been found in Treg cells of asthma patients; the imbalance of FOXP3 and GATA3 is an important cause of pathogenic alteration of Treg cells in asthma patients." (PMID 35846989, 2022). "After the identification of Th17 cells, we conducted WB analysis to detect RORγt and GATA3 in the animal and cellular severe asthma model." (PMID 36062195, 2022). "Human birth cohort studies have shown distinct methylation signatures of IL-4R and GATA3 genes being present at birth in children who developed asthma." (PMID 35693821, 2022). "In OVA-induced asthma model, Δpep27 immunization induces anti-inflammatory Treg transcription factor Foxp3, and represses allergic Th2 transcription factor (GATA-3)." (PMID 35484967, 2022). "OA, which is the major component of CP, reduced IgE binding to the allergens; Camellia japonica oil, which contains OA as the major bioactive component, suppressed asthma incidence through the GATA-3/Th2 cytokine pathways." (PMID 33806085, 2021). "In this study, we investigated the antiasthmatic effects of the CP and the involvement of the Th2/GATA-3 and IL-17/RORγt pathways in a mouse model of asthma." (PMID 33806085, 2021). "It has been reported that GATA-3-specific DNAzymes such as gd21 and hgd40 can significantly reduce GATA-3 mRNA expression and experimental asthma in vitro and in vivo." (PMID 33917396, 2021). "The authors reported that there were 15 pathways including IL4 and GATA3-related pathway in the multi-comorbidity of asthma, eczema, and rhinitis, and a number of proteins were obtained potentially related to this multi-comorbidity processes." (PMID 34212158, 2021). "GATA3+ Th2 cells have been observed in specimens from bronchoalveolar lavage and lung biopsies obtained from patients with severe asthma, even after continuous per oral corticosteroid." (PMID 33133517, 2020). "GATA3 demonstrates stronger regulation of its targets in the MHCI_1 module in asthma, but weaker regulation of its targets in the IL1 module." (PMID 32732938, 2020). "In human clinical studies, blocking GATA3 is able to control allergy responses, inflammatory diseases and asthma." (PMID 32045425, 2020). "Most recently, a GWAS on asthma severity with large-scale samples (N = 57,695) was reported, and several asthma severity risk genes were identified; such as MUC5AC, KIAA1109, and GATA3." (PMID 33066754, 2020).